SEPTIN9 (septin 9)
Diseases named in the same sentence as SEPTIN9 in open-access papers (continued):
Sharing a sentence is not in itself a finding about the gene and the disease.
cancer (continued). "Some TSGs, including GSTP1, MGMT, CDH1, P16, RAR-β2, septin 9 (SEPT9), syndecan 2 (SDC2), cyclin-dependent kinase inhibitor 2A (CDKN2A), and short stature homeobox 2 (SHOX2), have been validated to be silenced through DNA methylation in various types of cancer." (PMID 32075099, 2020).
tumor (117 papers, 2005 to 2026). "Research has indicated a direct association between Septin9 and tumor development, with varying expression and function across different tumor types." (PMID 39998886, 2025). "This gene encodes the septin-9 protein, which functions as a tumor suppressor." (PMID 39080571, 2024). "Indeed, overexpression induced the proliferative tumor phenotype with the lumen filling of MDCK cysts, and the loss of expression or deletion of two septin 9 PB domains induced the invasive tumor phenotype represented by the inverted polarized phenotype." (PMID 37508480, 2023). "A study found that hypermethylation of the CpG island in the promoter region of the septin-9 gene, which acts as a tumor suppressor gene, inhibited the normal expression of the gene and consequent loss of its tumor suppressor function, thereby promoting the development of CRC." (PMID 31088406, 2019). "This hypothesis is consistent with recent studies that show Septin 9 isoform over-expression is associated with an oncogenic phenotype and evidence that Septin 9 v1 over-expression is associated with tumor resistance to drugs that disrupt microtubule formation." (PMID 19018278, 2008). "The correlation between pre-treatment SEPTIN9 gene methylation ratio, tumor size, tumor stage and tumor response was analyzed." (PMID 40149300, 2025). "The development of the blood-based Septin9 methylation assay, the mqMSP assay, and new methylation assay targeting multiple different tumor suppressor genes, heralds a new era in CRC detection." (PMID 39080571, 2024). "Candidate analytical targets include cell-free DNA (cfDNA), methylated circulating tumour DNA (ctDNA), gene-specific methylated septin 9 (mSEPT9), and combinations of methylated DNA and proteins." (PMID 37749610, 2023). "This suggests that septin 9 expression, along with its assembly through the two PB domains, is essential for establishing and maintaining apico–basal polarity against tumor development." (PMID 37508480, 2023). "This study concluded that Septin 9 methylation levels were more sensitive to detect tumor recurrences than CEA levels." (PMID 35454041, 2022). "Although the time at which the second measurement occurred was not determined, it was reported that the patients without methylation of Septin 9 were disease-free and those cases positive for methylation of Septin 9 presented with tumor recurrences." (PMID 35454041, 2022). "Emerging screening strategies, such as ctDNA, circulating tumor cells, and septin-9, have been studied widely." (PMID 35480120, 2022). "Hypermethylated Septin9 fragments can be found in tumor DNA that passes into the bloodstream from all colonic anatomical segments." (PMID 34898591, 2021). "Septin-9 has also been implicated in cell proliferation, as a septin-9 variant SEPT9_i1 binds to c-Jun-N terminal kinase (JNK), preventing its degradation and therefore promoting tumor cell proliferation." (PMID 31105878, 2019). "Methylation of septin 9 (SEPT9) in tumor-derived cell-free DNA (cfDNA) is the only blood-based FDA-approved methylation biomarker for detecting CRC." (PMID 31261771, 2019). "In all five tissue groups, the level of the Septin-9 protein in stromal cells was comparable with the lowest Septin-9 level found in tumor samples." (PMID 23988185, 2013). "Multiplex qMSP analysis of Septin9, Epo, and MT-1A showed detection sensitivities of 85.49% (95% CI, 82.55%~88.01%) for overall (n = 641) patients, and the detection performance showed positive correlation with the tumor progression." (PMID 39998886, 2025). "To test this hypothesis, we conducted a Next-Generation Sequencing (NGS) analysis and measured the methylation status of multiple CpG-rich subregions in the Septin9 promoter from CRC tumor tissues, compared with their paired adjacent normal tissues." (PMID 39080571, 2024). "Patients with low expression of septin 9 in tumor tissue showed significantly poor DFS (P < 0.001)." (PMID 35227194, 2022).
tumor (continued). "Through the detection of spetin 9 protein in tumor tissues, we found that when septin 9 protein was low expressed in tumor tissues, its gene methylation level tended to be high in plasma, and low expression of septin 9 protein in tumor tissues was often associated with poor prognosis." (PMID 35227194, 2022). "Previous studies suggested that septin 9 protein played a tumor suppressive role in CRC." (PMID 35227194, 2022). "However, as the tumor progressed, more and more CpG islands of the septin 9 gene promoter were methylated, affecting its normal gene expression process." (PMID 35227194, 2022). "Low expression of septin 9 protein in tumor tissues was often related to poor prognosis." (PMID 35227194, 2022). "Septin 9 hypermethylation was present in 9 samples, matching 4 patients with tumor recurrence." (PMID 35454041, 2022). "In addition, methylation detection of Septin 9 gene in free DNA circulating in plasma, can predict tumor recurrences of CRC." (PMID 35454041, 2022). "Finally, they selected three of these markers (the genes HS3ST2, SLIT2 and SEPTIN9) for combination with the FGFR3 mutations in a logistic regression model, obtaining a sensitivity of 94.5% (96% in high-grade tumours) and a specificity of 75.9%." (PMID 32664878, 2020). "Quantitative DNA methylation levels for septin 9 (SEPT9) and short-stature homeobox 2 (SHOX2) in the ctDNA proved to be powerful prognostic and molecular staging biomarkers for identifying patients at a higher risk of tumour recurrence." (PMID 32415241, 2020). "Methylated Septin9 can be detected in tumor locations of colon and rectum." (PMID 30013949, 2018). "Among the most potential diagnostic biomarkers for CRC, the tumor specific M2 isoform of pyruvate kinase (PKM2) and tissue inhibitor of matrix metalloproteinase 1 (TIMP1), vimentin (VIM) and septin 9 (SEPT9) take a lead in being the most extensively investigated ones." (PMID 27844020, 2016). "Over-expression of Septin 9 isoforms has also been demonstrated in a number of tumor tissues." (PMID 19018278, 2008). "Additionally, for the CRC liver metastasis setting we found that DNA methylation markers investigated in cfDNA from liquid biopsies provided superior AUC values as the already established tumour marker Septin9, providing a rationale for implementing those markers in the clinical routine." (PMID 34698107, 2021). "SEPTIN-9 and CAPG consistently exhibited increased expression in both pathologies, indicating a shared structural organization in the cytoskeleton during tumour dormancy." (PMID 39223638, 2024). "On the other hand, methylated septin 9 (mSEPT9) (Epi proColon) is an FDA approved kit for the detection of DNA methylation marker, SEPT9, in circulating tumor DNA (ctDNA) in serum." (PMID 35292091, 2022). "Pre-treatment SEPTIN9 gene methylation ratio (p = 0.033) and tumor size (p = 0.026), but not tumor stage, significantly correlated with tumor response to total neoadjuvant therapy." (PMID 40149300, 2025). "Pre-treatment SEPTIN9 gene methylation ratio also correlated with N stage (p = 0.040) and tumor size (p = 0.001), but not with T stage (p = 0.846)." (PMID 40149300, 2025). "In addition, tumour cell pseudopod-specific proteins (AHNAK, Septin-9, eIF4E, and S100A11) were identified from the transcriptome/proteome analysis and closely for pseudopod formation, actin cytoskeleton dynamics, and tumour cell migration and invasion." (PMID 30504808, 2018). "Septin 9 is capable of interacting with the hypoxia-inducible factor 1 alpha HIF-1α acting as a positive regulator in the hypoxic pathway leading to increased proliferation, soft agar clonal survival and tumor growth." (PMID 29699512, 2018). "Similarly, SEPTIN9 participates in cytokinesis during the cell cycle, while SHOX2 is a transcription factor involved in proliferation, migration and colony formation and MGMT inhibits tumour formation." (PMID 38903861, 2024).
tumor (continued). "However, Septin 9 methylation rates were not related to tumor T classification (T1-2 vs. T3-4) (p = 0.78)." (PMID 32454907, 2020). "As we observed a common overexpression of SEPTIN9 and CAPG at the protein level in dormant cells regardless of the tumour type, we investigated a potential functional impact by measuring the physical properties of the dormant cells compared to their parental counterpart cells in both MRD models." (PMID 39223638, 2024). "However, no serum tumour markers have approved screening utility for CRC, and although a recently evaluated plasma septin 9 (SEPT9) DNA methylation test (Epi proColon) holds some promise, increased uptake (vs faecal testing) in non-compliant populations needs to be demonstrated." (PMID 26035703, 2015).
gastrointestinal tumors (2 papers, 2023 to 2025). "Particularly, Septin9 is highly expressed in gastrointestinal tumors, serving as a reliable marker for their detection." (PMID 39998886, 2025).
infection (2 papers, 2016 to 2024). The state of being infected such as from the introduction of a foreign agent such as serum, vaccine, antigenic substance or organism. "Treatment of Huh7.5 cells with two different septin 9 siRNAs (si1 and si3) before their infection strongly reduced core expression." (PMID 27417143, 2016). "Thus, the targeted release of Septin-9 by infected cells may represent a mechanism whereby the pathogen manipulates the host response to evade clearance during infection." (PMID 38907250, 2024).
SEPTIN9 also shares sentences with these, for which no sentence is quoted: head and neck squamous cell carcinoma (11 papers); glioblastoma (6); glioma (6); hepatocellular carcinoma (6); colorectal adenoma (5); head and neck cancer (5); breast tumors (4); ovarian tumors (4); pancreatic cancer (4); adenocarcinoma (3); diabetes (3); liver cancer (3); bacterial infection (2); bladder cancer (2); breast adenocarcinoma (2); cholangiocarcinoma (2); colitis (2); colorectal polyps (2); epithelial dysplasia (2); esophageal cancer (2); Lynch syndrome (2); metastatic disease (2); metastatic melanoma (2); neurodevelopmental disorder (2); Obesity (2); peripheral neuropathy (2); Sepsis (2); Type 2 Diabetes (2); acute lymphoblastic leukemia (1); acute myeloid leukemia (1).
A further 65 diseases each share a sentence with SEPTIN9 in 1 paper.